CD4 (CD4 molecule)
Diseases named in the same sentence as CD4 in open-access papers (continued):
Sharing a sentence is not in itself a finding about the gene and the disease.
Sepsis (continued). "In this study, we found that neutrophil extracellular traps (NETs) participated in the development of sepsis-induced immunosuppression by enhancing Treg differentiation and function via direct interaction with CD4+ T cells." (PMID 40892462, 2025). "Accumulating evidence from both clinical and preclinical studies suggests a causal link between T cell dysfunction and immune dysregulation in sepsis characterized by reduced CD4+ T cell counts and proliferative activities." (PMID 40995563, 2025). "Proliferative activity of CD4+ T lymphocytes in sepsis was assessed using cell counting kit-8 (CCK-8), showing a significant decrease in proliferation following LPS stimulation or CLP in both the Flox and cKO groups." (PMID 40995563, 2025). "Studies have shown that patients who succumb to sepsis exhibit marked immunosuppression, characterized by significant reductions in immune cells, such as CD4+ and CD8+ T cells, in the spleen or lungs." (PMID 40779122, 2025). "Neutralizing IL-10 or TGF-β, which are key in Treg differentiation, can alleviate immunosuppression in sepsis, reduce the ratio of Tregs to CD4+ T cells, and restore the number of CD4+ T cells in the spleen, potentially increasing survival." (PMID 40153575, 2025). "Within 2 to 4 days of the onset of sepsis, lymphocyte apoptosis and substantial decreases in CD4+ and CD8+ T cells occur." (PMID 40153575, 2025). "Decreased percentages of CD4 T cells and less diverse T-cell receptor repertoires were reported in pediatric sepsis patients." (PMID 40755920, 2025). "Univariate logistic regression results indicated that the expression level of miR-146b-5p, CD3%, CD4%, APACHE II scores, and SOFA scores were independent risk factors for sepsis prognosis (p = 0.003, 0.002, 0.037, 0.001, 0.001)." (PMID 40642098, 2025). "The logistic regression analysis and Cox regression analysis were used to evaluate the predictive value of serum miR-146b-5p, APACHE II scores, CD3%, and CD4% levels for the prognosis of patients with sepsis." (PMID 40642098, 2025). "The sepsis cohort, compared to healthy, had a higher proportion on Day 1 of CD4+ T cells expressing regulatory markers (CD45RA+/FoxP3+) (22% vs 12% of CD4+, p=0.01)." (PMID 39935482, 2025). "For further confirmation, we ascertain the effect of Th1 on DOCK2-deficient mice in LPS-induced sepsis by blocking IFN-γ and depleting CD4+ T cells in vivo." (PMID 40510337, 2025). "Firstly, our study is contextualized within CD4+ T cell responses, reflecting their dominant role in sepsis pathogenesis." (PMID 40995563, 2025). "Timothy Buchman’s research team discovered through experiments that CD4+ T lymphocytes are key factors in regulating intestinal epithelial cell survival and host prognosis in sepsis." (PMID 41472805, 2025). "Then, WB was utilized to evaluate the impact of SN-011 on the CD4+ T lymphocyte signaling pathway and PANoptosis-related protein expression during sepsis." (PMID 40995563, 2025). "This clinical study demonstrates that CHOP and GRP78 expression on CD4+ T lymphocyte is significantly higher in sepsis patients, indicating that ERS was much more enhanced." (PMID 40933998, 2025). "We first identified the proviral integration site for Moloney murine leukemia virus 1 (PIM1) as a significantly upregulated gene in CD4+ T cells from sepsis patients by conducting a comprehensive transcriptome meta-analysis." (PMID 40899834, 2025). "In sepsis, age positively correlated with the percent of CD4+ cells that were regulatory (CD45RA+FoxP3+), r2 = 0.32, p=0.002." (PMID 39935482, 2025). "Collectively, these results reveal significant changes in the number and function of peripheral immune cells in sepsis patients, especially the reduction of CD4+ T cells." (PMID 41306770, 2025). "Ulteriorly, we verified the vital role of DOCK2-mediated Th1 cells in sepsis by neutralizing both IFN-γ and CD4 and found both of which blockade reduced the severity of sepsis in Dock2−/− mice." (PMID 40510337, 2025).
Sepsis (continued). "Further, a higher number of IL-10-producing and lower number of TNF-producing CD4+ T cells in PLN substantiate the idea that immunoregulatory surroundings prevail in lymphoid organs after sepsis." (PMID 41142792, 2025). "Correlation analysis between 14 CRGs and immune cells in sepsis-associated ALI showed that DLD was significantly positively correlated with eosinophils, resting NK cells, and activated CD4+ memory T cells." (PMID 38779731, 2025). "Glucose transporter 1 (GLUT1), a key protein for aerobic glycolysis, is decreased in CD4+ T cells of sepsis." (PMID 41158471, 2025). "Significant differences in immune cell infiltration were observed between sepsis and healthy control groups, particularly in activated B cells and CD4 T cells." (PMID 40861493, 2025). "The largest increase in Th proportions in sepsis compared to control samples was in the population of CD69+ naïve CD4+ T cells (1.99log2FC)." (PMID 41208955, 2025). "The sepsis dataset revealed a substantial elevation in the level of activated mast cells, while the levels of naive CD4 + T cells and resting mast cells were dramatically diminished." (PMID 40781631, 2025). "During sepsis, CD4+ T cells can differentiate into regulatory T lymphocytes (Tregs) and suppress the immune response." (PMID 40153575, 2025). "We further isolated CD4+ T cells from sepsis patients using flow cytometry to analyze their functional impairment." (PMID 41306770, 2025). "Comparative analysis of immune cell proportions between sepsis patients and healthy controls demonstrated significant shifts: B cells, Macrophages, CD4+ T cells, CD8+ T cells, and NK cells were reduced in sepsis patients, whereas neutrophils were elevated." (PMID 41332909, 2025). "The influence of ARG2 inhibition on CD4+ T cell functionality in vivo was further explored to delineate its role in sepsis immunopathology." (PMID 40860137, 2025). "Contrastingly, the CD45RA−17A+CD4+ T cells were significantly increased in those with sepsis in both age groups." (PMID 40433376, 2025). "The CD15+CD14+ monocytes and CD45RA−CX3CR1+CTLA4+CD4+ T cells were only significantly increased in children with sepsis in those >1 year of age." (PMID 40433376, 2025). "EGFR in CD4+ T cells also regulates inflammation (e.g., limiting IL‐17‐mediated pathology) and promotes apoptosis in sepsis via Glut1 translocation." (PMID 40859900, 2025). "There were strong associations between sepsis events and the expression levels of GPX4 in classical and alternative monocytes, as well as PRDX4 in naïve CD4+ T cells and GR in naïve CD8+ T cells." (PMID 40593569, 2025). "The impact of NUFIP1-mediated ribophagy on CD4+ T lymphocyte PANoptosis in sepsis was investigated by establishing a lentiviral transfection model in Jurkat T cells." (PMID 40995563, 2025). "The largest proportional increase in sepsis patients compared to controls was evident in CD69+ naïve CD4+ T cells." (PMID 41208955, 2025). "We observed significantly reduced NFAT protein levels in peripheral CD4+ T cells from sepsis patients compared to those in healthy donors." (PMID 41306770, 2025). "Experimental models indicate that β1AR activation suppresses CD4+ T cell function in sepsis, leading to immune exhaustion." (PMID 40421209, 2025). "Children with sepsis had more regulatory CD4+ T cells and memory CD4+ T cells and less CD4+IL-10+ and CD8+T-bet+ T cells than healthy children." (PMID 39935482, 2025). "to clarify the endoplasmic reticulum stress (ERS) status of CD4+ T lymphocytes in sepsis patients, particularly elderly individuals aged over 65 years, and to elucidate its association with mTOR-mediated autophagic-lysosomal disorder." (PMID 40933998, 2025). "In the current study, we found that NUFIP1-mediated ribophagy modulated CD4+ T lymphocyte PANoptosis in sepsis, consequently augmenting T cell-mediated immunity and preserving systemic immune homeostasis." (PMID 40995563, 2025).
Sepsis (continued). "Decreased CD4 cell counts (941 cells × 106/L, normal range 2330 to 3617 cells × 106/L) and recurrent infections (pneumonia, otitis media, sepsis, dermatitis, and diarrhea) were also observed in patients in our study." (PMID 41204599, 2025). "Prior studies on the impact of sepsis on naïve CD4+ and CD8+ T cells demonstrated a reduction in the frequency of naïve T cells during potent inflammation." (PMID 39866877, 2025). "Increases in Th subsets were mirrored in comparisons of sepsis samples to bacteraemia samples with higher levels of naïve CD4+ T cells (1.6log2FC), Th17 cells (0.76log2FC), and central memory (CM) CD4+ T cells (0.59log2FC)." (PMID 41208955, 2025). "During sepsis, IL-7R levels increase, particularly on CD4+ and CD8+ T cells, and remain elevated for 1–4 days." (PMID 41158471, 2025). "Sepsis patients had higher regulatory CD4+ T cells but an overall more pro-inflammatory plasma cytokine milieu and higher levels of TEMRA CD8+ T cells." (PMID 39935482, 2025). "Abdominal infections, especially sepsis, result in a surge of pro‐ and anti‐inflammatory cytokines, leading to chronic immunoparalysis characterized by impaired CD4 and CD8 αβ T cell responses in the post‐septic environment." (PMID 39835710, 2025). "As a central player in adaptive immunity, CD4+ T cells are crucial for maintaining this balance during sepsis by differentiating into various effector T cell subsets." (PMID 40899834, 2025). "CD4+ T cells, particularly memory cells, undergo significant depletion during the acute phase of sepsis." (PMID 40124361, 2025). "The higher modularity in the paediatric sepsis network is attributed to the formation of a restricted communication module between CD4+ and CD8+ T-cell subsets with each other." (PMID 40433376, 2025). "Paradoxically, baseline intracellular calcium levels were elevated in CD4+ T cells from sepsis patients, despite reduced NFAT dephosphorylation." (PMID 41306770, 2025). "The development of sepsis is also linked to a notable reduction in lymphocytes, characterized by a decrease in the count of CD8, CD4, B cells, and NK cells." (PMID 40070882, 2025). "In the context of sepsis immune monitoring, several basal-state biomarkers (i.e. without prior stimulation) are routinely used in clinical practice, such as mHLA-DR, CD4+/CD8+ ratio, and circulating IL-10." (PMID 40796210, 2025). "The expression of PIM1 was significantly elevated on CD4+ T cells from sepsis patients and was correlated with both SOFA and APACHE II scores." (PMID 40899834, 2025). "Our previous research identified mTOR as a key regulator of T cell metabolism and demonstrated its role in modulating ERS-induced CD4+ T cell apoptosis during sepsis." (PMID 40933998, 2025). "After ex vivo stimulation, sepsis samples had less of a reduction in CD4+ T cells producing IL-10 than healthy controls." (PMID 39935482, 2025). "The Western blot (WB) results confirmed a significant elevation in the expression of CD4+ T lymphocyte PANoptosis-related protein in the sepsis group compared to the control group." (PMID 40995563, 2025). "MAIT cell frequencies declined in sepsis patients compared with healthy controls, while the frequencies of CD4+, CD8+ or DN non‐MAIT T cells remained unchanged." (PMID 40041474, 2025). "Our findings establish MMP9 as a critical regulator of CD4+ T cell dysfunction in sepsis, acting primarily through disruption of TCR signaling and intracellular calcium homeostasis." (PMID 41306770, 2025). "There was a progressive increase in the frequency of the CD15+CD14+ monocytes, CD45RA−17A+CD4+ T cells, and CD45RA-CX3CR1+CTLA4+CD4+ T-cell subsets from control to sepsis with organ dysfunction." (PMID 40433376, 2025). "CD15+CD14+ monocytes, CD45RA−17A+CD4+ T cells, CD45RA−CX3CR1+CTLA4+CD4+ T cells, and Ki67+ B cells were significantly increased in patients with sepsis, with the CD15+CD14+ monocytes having the largest normalised effect size in sepsis." (PMID 40433376, 2025).
Sepsis (continued). "Results showed that, compared to healthy controls, CD4+ T cells co-cultured with sepsis patient serum exhibited significantly increased apoptosis rates." (PMID 41306770, 2025). "In this study, we found that NETs contributed to sepsis-induced immunosuppression by promoting the differentiation and function of Tregs via direct binding to CD4+ T cells." (PMID 40892462, 2025). "During sepsis, CD4+ T cells undergo the highest levels of apoptosis, a process closely linked to patient survival." (PMID 40005375, 2025). "Beyond neutrophils, lymphocyte apoptosis, particularly involving B and CD4+ T cells, is considered a key factor in sepsis-induced immune suppression." (PMID 40817040, 2025). "In contrast, RBBP7 is downregulated in sepsis and demonstrates positive correlations with activated NK cells and memory CD4+ T cells." (PMID 41394771, 2025). "Transmission electron microscopy (TEM) illustrated that CD4+ T lymphocytes from the sepsis group displayed distinct morphological features indicative of pyroptosis, apoptosis, and necrotic apoptosis." (PMID 40995563, 2025). "Next, Cd4creNufip1fl/fl mice were utilized to explore the influence of conditional NUFIP1 knockout on CD4+ T cell immune function, multi-organ damage, and prognosis in sepsis." (PMID 40995563, 2025). "We identified 3 sepsis subtypes with marked different prognostic characteristics, with the C1 subtype showing the worst prognosis characterized by severe CD4+ T cell exhaustion—validated across 10 independent cohorts." (PMID 41306770, 2025). "Further, CD4+IL10+ T cells, including IL10+ regulatory CD4 T cells, were lower in sepsis compared to healthy patients." (PMID 39935482, 2025). "The AUC values for miR-146b-5p, APACHE II scores, CD3%, and CD4% in predicting the prognosis of sepsis patients were 0.691, 0.761, 0.633, and 0.611, respectively." (PMID 40642098, 2025). "Despite growing evidence linking PANoptosis to the pathogenesis of various diseases, the potential role of ribophagy in modulating CD4+ T lymphocytes’ PANoptosis in sepsis remains largely unclear." (PMID 40995563, 2025). "The expression of CD4+ and CD8+ T cells in the LP was significantly decreased among sepsis exposed mice compared to controls (CD4+ T cells p = 0.006; CD8+ T cells p = 0.0004)." (PMID 40557325, 2025). "In this section, we found higher DDR levels in sepsis than in controls, with CD4+ T cells, monocytes, megakaryocytes, and neutrophils showing the highest DDR, and observed an association between lower DDR scores and poorer sepsis prognosis." (PMID 38404591, 2024). "It has been demonstrated that EGFR regulates the inflammatory function of macrophages, and EGFR can also induce the apoptosis of CD4(+) T lymphocytes through the TBK1/Glut1-induced Warburg effect in sepsis." (PMID 38632608, 2024). "In sepsis, CD4+ T-cell numbers, phenotypes, and functions are relatively different, which is the leading cause of immunosuppression." (PMID 39104632, 2024). "As sepsis progressed, splenic Siglec-F+ neutrophils were gradually increased, while the activity of CD4+ and CD8+ T lymphocytes was decreased." (PMID 38646647, 2024). "In CLP-induced sepsis, CD4+ T cells from TIGIT-/- mice shown increased proliferation potency and cytokine production when compared with that from WT mice." (PMID 38545097, 2024). "Focusing on the expression and signaling networks of these negative regulatory molecules can definitely provide emerging directions for preserving CD4+ T cells for the treatment of sepsis." (PMID 39104632, 2024). "By combining these two analytical methods, we found that the low expression of LGALS9 in sepsis patients is associated with the activation and differentiation of CD14+ monocytes and CD4+‐naive T cells." (PMID 39044269, 2024). "Patients suffering from ARDS and sepsis had elevated levels of monocytes, neutrophils, and naive CD4 T cells, while those with only sepsis had higher counts of CD8+ T cells and resting NK cells." (PMID 39763654, 2024).
Sepsis (continued). "Since T cell subsets experienced significant cell composition and phenotypic alterations in elderly patients with sepsis, we further performed trajectory and pseudotime analyses to study the differentiation of CD4 + and CD8 + T cells via Monocle." (PMID 38909272, 2024). "The objective of this study was to investigate the role of miR-223 in regulating autophagy and immune function in CD4+ T lymphocytes during sepsis, and to elucidate the mechanisms through which miR-223 contributes to the pathophysiology of sepsis." (PMID 39439897, 2024). "The present results have shown the dynamics change of CD4+ T lymphocytes on study days 1, 2, 4, and 7 of some patients with sepsis." (PMID 39290582, 2024). "Following induction of CLP-induced sepsis, increased IL-21 production was indicative of increased functionality in CD4+ TFH cells, which in turn were able to reverse the sepsis-induced decline in splenic B cells seen in controls." (PMID 38197178, 2024). "In sepsis, there is a noticeable occurrence of apoptosis in immune cells including CD4 T cells, CD8 T cells, B cells, natural killer (NK) cells, and follicular dendritic cells." (PMID 39267971, 2024). "The sepsis group showed an elevation in monocytes, macrophages, and neutrophils, alongside a decrease in Memory B cell, CD4+T cells, and CD8+T cells." (PMID 39364223, 2024). "Patient 7, who had an HIV load < 50 copies/ml but a low CD4 T-cell count before LT, died of multiple organ failure from bacterial infection and sepsis 66 days after LT." (PMID 38589801, 2024). "Regulation of the autophagy in CD4+ T lymphocytes by miR-223 establishes a potential target for treating sepsis." (PMID 39439897, 2024). "This suggests that with the progression of the disease, the continued decline in CD4+ T lymphocyte counts is indicative of a poor prognosis of sepsis patients." (PMID 39290582, 2024). "(b) Compared to sepsis survivors, deceased patients have lower counts of effector T cells (mostly observed in CD4+ T cells)." (PMID 38339179, 2024). "In stark contrast, sepsis patients demonstrated reduced populations in the adaptive immunity sector, characterized by a decline in naive CD4 T-cells, CD8 T-cells, and memory B cells." (PMID 39331858, 2024). "CTLA-4+ Treg (CD3+CD4+CD25+CD127-FOXP3+CTLA-4+) frequencies and CTLA-4 expression were significantly higher in neonates with clinical sepsis compared to healthy subjects with prenatal risk factors." (PMID 39072327, 2024). "In the sepsis group, Neutrophil displayed strong interaction strength and large interaction number with CD4+ T cell, CD8+ T cell, NK cell, B cell, macrophage, megakaryocyte, DC, mast cell, monocyte, plasma, and Neutrophil." (PMID 39108261, 2024). "One of the most damaging consequences of septicemia is the development of apoptosis that dramatically reduces CD4+ cell populations." (PMID 38474403, 2024). "T lymphocyte dysfunction after sepsis is characterized by an increased proportion of a CD4+CD25+CD127low regulatory T cell subpopulation among circulating patients’ lymphocytes due to a decrease of effector T cell numbers." (PMID 38474403, 2024). "T cells appear to be disproportionately affected by sepsis with CD4+ T cells known to decline to levels seen in patients with AIDS." (PMID 38197178, 2024). "Peripheral blood samples were collected from sepsis patients after burns, and Treg cells were isolated using a CD4+CD25+ regulatory T cell isolation kit." (PMID 38339179, 2024). "CD4+ T cell immunity against polymicrobial infection during CLP-induced sepsis was enhanced by genetic ablation or antibody blockade of TIGIT." (PMID 38545097, 2024). "This study proves that miR-223 participate in the regulation of LPS-induced autophagy via the regulation of FOXO1 expression in CD4+ T lymphocytes which shed a new light for the diagnosis and treatment of sepsis." (PMID 39439897, 2024).